ERCC2 (ERCC excision repair 2, TFIIH core complex helicase subunit)
Diseases named in the same sentence as ERCC2 in open-access papers (continued):
Sharing a sentence is not in itself a finding about the gene and the disease.
bladder cancer (continued). "Finally, in vitro cell behavioral assays determined that knockdown of ERCC2 gene expression significantly inhibited the proliferation, migration and invasion of bladder cancer cells." (PMID 39192988, 2024). "As expected for bladder cancer, we commonly observed single-base substitution 2 (SBS2) and SBS13 (both characteristic of APOBEC3 mutagenesis, N=13 cases) and SBS5 (associated with smoking history and ERCC2 mutations, N=11 cases)." (PMID 36961501, 2023). "When we investigated the effect of genetic polymorphisms in bladder cancer development we have found that ERCC2 and ERCC5 variants were not implicated in the bladder cancer occurrence." (PMID 21426550, 2011). "To test this hypothesis, we genotyped Lys939Gln genotype (A > C; rs2228001), ERCC2 Lys751Gln (rs13181) and ERCC5 Asp1104His (G > C; rs17655) polymorphisms in our ongoing hospital-based case-control study of Bladder cancer in a population from Tunisia." (PMID 21426550, 2011). "There is reason to believe that ERCC2 may be a potential therapeutic target for bladder cancer." (PMID 39192988, 2024). "Recently, it was shown that mutations in the NER helicase gene ERCC2 detected in urothelial carcinoma of the bladder cause NER deficiency in cell line models and that ERCC2 mutations are associated with platinum sensitivity in some bladder cancer clinical cohorts." (PMID 37996508, 2023). "Our study revealed a favorable correlation between the expression of ERCC2 and ERCC6 in patients with bladder cancer (BLCA) and the BLCA stem cell index." (PMID 39192988, 2024). "We have demonstrated that ctDNA profiling can identify previously proposed biomarkers for therapy response in bladder cancer, including alterations in FGFR3, ERCC2, and ERBB2, and TMB." (PMID 33420073, 2021). "ERCC2 N238S was observed seven times in GENIE and five of those samples were bladder cancer." (PMID 30709382, 2019). "While this approach clearly demonstrated a cisplatin sensitizing effect of clinically observed ERCC2 HD mutations, it does not fully recapitulate the genetic context of bladder cancer because most ERCC2-mutant bladder tumors harbor a heterozygous missense ERCC2 mutation without accompanying LOH." (PMID 40829180, 2025). "Of note, we found that ERCC2 alterations (which are recurrently found in bladder cancer) co-occur significantly with POLD2 expression (P = 0.010; data not shown), but not with CAD expression, suggesting POLD2 as putative gene of interest in future studies examining ERCC2." (PMID 30038717, 2018).
lung carcinoma (39 papers, 2005 to 2025). "At present, an experiment conducted in Japan has demonstrated that the ERCC2 Lys751Gln polymorphism is associated with an increased risk of lung cancer." (PMID 40777111, 2025). "The ERCC2 gene exhibits high levels of genetic polymorphism and has been associated with increased susceptibility to various types of cancer, including lung cancer, hepatocellular carcinoma, and malignant melanoma." (PMID 40777111, 2025). "For example, two haplotypes containing the ERCC2 rs3916874 G allele were closely related to the risk of lung cancer, rs13181-rs3916874-rs238415 AGG haplotypes are associated with an increased risk of pancreatic cancer." (PMID 34284736, 2021). "Both ERCC1 and ERCC2 have SNP loci associated with quality of life, anxiety and depression in lung cancer, mainly focusing on ERCC1rs11615 and rs3212986, associated with multiple domains of quality of life." (PMID 34284736, 2021). "There are few studies on the relationship between single nucleotide polymorphisms (SNPs) of ERCC1 and ERCC2 and QoL in lung cancer patients." (PMID 34284736, 2021). "Both ERCC1 and ERCC2 haplotypes are associated with multiple domains of quality of life in lung cancer patients." (PMID 34284736, 2021). "This was the only study ever published about the ERCC2 rs50872 polymorphism and lung cancer prognosis." (PMID 27465648, 2016). "Comparison of p-values for the mutual information-based statistics and logistic regression to the interaction between ERCC2 polymorphisms and smoking in lung cancer." (PMID 19238204, 2009). "Both the mutual information-based statistics and logistic regression analysis were used to test interaction between the polymorphism of ERCC2 and smoking in lung cancer." (PMID 19238204, 2009). "However, an Asian lung cancer study recently reported that ERCC2 rs13181 TG and TG + GG genotypes were significantly linked to worse OS under a dominant model." (PMID 40526606, 2025). "Her family cancer history review demonstrated that her two healthy sisters, a brother with lung cancer, and three healthy cousins were positive for ERCC2 frameshift mutation, which might contribute to increased cancer risk." (PMID 37223679, 2023). "A study found that signature 5 is associated with DNA repair gene ERCC2 mutations in urothelial tumors, which may be used for reference to lung cancer research." (PMID 34642306, 2021). "As few studies have explored the genetic factors affecting the quality of life, we first proposed the correlation between ERCC1, ERCC2 gene polymorphisms, and the quality of life of lung cancer patients, which provides a new perspective for the study of LC patients’ quality of life." (PMID 34284736, 2021). "Interestingly, two meta-analyses reported that SNPs in both ERCC1 and ERCC2 genes may play a significant role in lung cancer risk." (PMID 39735668, 2025). "In addition, the ERCC2 gene could also increase the risk of hepatocellular carcinoma, acute lymphoblastic leukemia, lung cancer and melanoma." (PMID 28223548, 2017). "Therefore, ERCC1 and ERCC2 SNPs may be associated with the QoL of lung cancer patients." (PMID 34284736, 2021). "It has been proved that polymorphisms of DNA repair genes, such as the polymorphisms of XPA ‐4G>A (rs1800975), ERCC2 862G>A (rs1799793) 12, MSH3 3133G>A (rs26279), and PMS1 639G>A (rs5742938) 13, are associated with the risk of lung cancer." (PMID 27335251, 2016). "In summary, we have fine-mapped the sub-region encompassing ERCC2, PPP1R1, CD3EAP and ERCC1 on chromosome 19q13.3 region in relation to lung cancer susceptibility among Chinese." (PMID 27183913, 2016). "ERCC2 rs13181 and ERCC1 rs3212986 SNPs have an elevated association with lung cancer risk 2, 11, while the O6-methylguanine-DNA methyltransferase gene SNP rs12917 is associated with an increased risk of lung cancer." (PMID 35069899, 2022).
lung carcinoma (continued). "SNPs of ERCC1 and ERCC2 genes may affect the protein expression level and activity and affect the resection and repairability of the NER system, which are related to lung cancer susceptibility, chemotherapy effect and toxicity of platinum drugs, and prognosis of lung cancer." (PMID 34284736, 2021). "However some reports found the non-correlation between the polymorphisms of ERCC2 gene and risk of lung cancer or the opposite results." (PMID 20003391, 2009). "Proteins that play a crucial role in this pathway, including excision repair cross-complementing group 1 (ERCC1), ERCC2, and ERCC5 have been widely studied in different types of tumors, including lung cancer." (PMID 39735668, 2025). "Although many genes, such as CYP1A1, ERCC2, and L10, have been confirmed to relate to nonsmoking lung cancer, the mechanism related to nonsmoking female lung cancer patients is not clear." (PMID 34671675, 2021).
trichothiodystrophy (33 papers, 2008 to 2025). Trichothiodystrophy or TTD is a heterogeneous group disorders characterized by short, brittle hair with low-sulphur content (due to an abnormal synthesis of the sulfur containing keratins). "This study reports a novel case of trichothiodystrophy (TTD) linked to compound heterozygous ERCC2 variants, presenting with progressive cerebral hypomyelination." (PMID 39976384, 2025). "Clinical/genetic findings in trichothiodystrophy (TTD) patients with myelination disorders caused by ERCC2 variants." (PMID 39976384, 2025). "Previous studies showed that mutations in ERCC2/XPD resulted in beta-thalassemia in patients with trichothiodystrophy." (PMID 36065184, 2022). "Trichothiodystrophy (TTD) mice have a mutation in the Ercc2 DNA repair gene, resulting in accumulation of DNA damage and several features of segmental accelerated aging." (PMID 22506075, 2012). "Moreover, biallelic mutations in ERCC2 can also lead to photosensitive trichothiodystrophy." (PMID 39244550, 2024). "Trichothiodystrophy (TTD) is a rare, autosomal recessive, multisystem disorder most commonly caused by variants in ERCC2." (PMID 33711971, 2021). "Trichothiodystrophy with ERCC2 and ERCC3 mutations is caused by defective DNA repair after UV damage, and hypomyelination was reported in trichothiodystrophy with ERCC2 mutation." (PMID 29451896, 2018). "Defects in the ERCC2 gene can result in three different disorders: the cancer-prone XPD syndrome, trichothiodystrophy, and aging disorders Cockayne syndrome, which is characterized by severe growth defects, mental retardation, and cachexia." (PMID 21496236, 2011).
xeroderma pigmentosum group D (26 papers, 2005 to 2025). Any xeroderma pigmentosum in which the cause of the disease is a mutation in the ERCC2 gene. "ERCC2 encodes xeroderma pigmentosum group D, and is involved in the nucleotide excision repair pathway." (PMID 40994809, 2025). "ERCC2 is associated with xeroderma pigmentosum group D (MIM: 278730) in an autosomal recessive manner." (PMID 39244550, 2024). "Biallelic germline mutations in ERCC2 are associated with the rare autosomal recessive disorder, xeroderma pigmentosum group D (XPD)." (PMID 38028607, 2023). "The human xeroderma pigmentosum group D gene XPD (also named ERCC2) encodes an adenosine triphosphate (ATP)–dependent 5′-3′ helicase of 760 amino acids." (PMID 35977011, 2022). "Excision repair cross-complementing rodent repair deficiency complementation group 2/xeroderma pigmentosum group D (ERCC2/XPD) plays a crucial role in the etiology of colorectal cancer (CRC)." (PMID 33809839, 2021). "The excision repair cross-complementing rodent repair deficiency, group 2 (ERCC2) gene, also called the xeroderma pigmentosum group D (XPD) gene, is located at chromosome 19q13.3." (PMID 24619222, 2014). "Potential xeroderma pigmentosum group D (XPD), also called excision repair cross-complimentary group two (ERCC2), Lys751Gln and Asp312Asn polymorphisms have been implicated in gastric cancer risk among different ethnicities." (PMID 23028453, 2012). "ERCC2 is a DNA repair gene involved in the nucleotide excision repair pathway, which encodes the DNA helicase XPD (xeroderma pigmentosum group D)." (PMID 39684352, 2024). "The DNA helicase encoded by the excision repair cross-complementing group 2 gene (ERCC2), also called xeroderma pigmentosum group D (XPD), is involved in basal cellular transcription and NER of DNA lesions." (PMID 33171788, 2020). "The xeroderma pigmentosum group D (XPD) gene, also known as ERCC2, encodes a 5′–3′ superfamily 2 helicase that plays a key role in unwinding the DNA double helix around damaged DNA during nucleotide excision repair (NER)." (PMID 30100919, 2018). "Among the polymorphic genes, excision repair cross-complementing group 2 (ERCC2), also called xeroderma pigmentosum group D (XPD), plays important roles in the nucleotide excision repair (NER) pathway." (PMID 28489582, 2017). "ERCC2 (MIM 126340) variants cause TTD1 (MIM 601675) and are also responsible for cerebrooculofacioskeletal syndrome (MIM 610756) and xeroderma pigmentosum group D (XPD; MIM 278730)." (PMID 26880286, 2016). "The aim of the present meta-analysis is to evaluate the effect of excision repair cross-complementing 2 (ERCC2, also known as XPD, xeroderma pigmentosum group D ) polymorphisms on radiotoxicity." (PMID 26627042, 2015). "The major component of NER, xeroderma pigmentosum group D (XPD or ERCC2), mapped in chromosome 19q13.3, spans over 20 kb, contains 23exons and encodes the 761-amino acid protein." (PMID 24787743, 2014). "Amongst the known genetic polymorphisms of the DNA-repair genes, the xeroderma pigmentosum group D (XPD, also known as ERCC2) and x-ray repair cross-complementing groups 1 and 3 (XRCC1 and XRCC3) have been studied most commonly." (PMID 15679883, 2005). "The xeroderma pigmentosum group D (XPD, also named excision reair cross-complementing group 2, ERCC2) gene encodes for an ATP-dependent DNA helicase, a subunit of the basal transcription factor II H (TFII H) which mediates DNA unwinding for the initiation of NER." (PMID 24260311, 2013).
Cockayne syndrome (23 papers, 2008 to 2025). A multisystem condition characterized by short stature, a characteristic facial appearance, premature aging, photosensitivity, progressive neurological dysfunction, and intellectual deficit. "Besides these major forms, several cases with specific minor mutations in ERCC3/XPB, ERCC2/XPD, and ERCC5/XPG display the combined features of XP and an orphan progeroid disorder, Cockayne syndrome (CS), termed XPCS." (PMID 37364129, 2023).
ovarian carcinoma (23 papers, 2008 to 2025). A malignant neoplasm originating from the surface ovarian epithelium. "In summary, the ERCC2 Lys751Gln polymorphism is associated with an increased risk of gynecological tumors, particularly ovarian cancer." (PMID 40777111, 2025). "The ERCC2 Lys751Gln polymorphism is associated with an increased risk of gynecological tumors, particularly ovarian cancer." (PMID 40777111, 2025). "This study found that there is an association between ERCC2 gene Lys751Gln polymorphism and increased risk of gynecological tumors, particularly increasing the risk of ovarian cancer." (PMID 40777111, 2025). "The wet lab analysis of PRKCG SNP rs1331232028, like many other SNPs in multiple genes, including ERCC1, XPC, PIK3CA, ERBB2 and ERCC2, can be linked to ovarian cancer susceptibility." (PMID 36672978, 2023). "ERCC2 single nucleotide polymorphisms (SNPs) were found to be associated with an increased risk of ovarian cancer." (PMID 35769257, 2022). "Vella et al19has suggested that low ERCC2 expression is associated with increased chemotherapeutic sensitivity and thus considered a predictive marker for patients with ovarian cancer receiving combination of gemcitabine and cisplatin chemotherapy." (PMID 33693445, 2020). "As a result, we found that both variant genotypes of XPC rs2228001 A>C and ERCC2 rs238406 G>T as well as ERCC1 rs3212986 C>A had a significant association with the increased risk of ovarian cancer under dominant and recessive genetic model respectively." (PMID 29669843, 2018). "Mutations and rare variants in ERCC2 identified through panel sequencing of individuals with familial breast and/or ovarian cancer." (PMID 27504877, 2016). "Recent studies explored XRCC2 rs3218536 and ERCC2 rs13181 polymorphisms and ovarian cancer (OC) risk." (PMID 27863412, 2016). "The Chinese researchers found also the association between ovarian cancer and ERCC2 Lys751Gln polymorphism." (PMID 26526682, 2015). "The aim of this study was to analyze the frequency of alleles and genotypes of Lys751Gln (rs13181) in ERCC2 with an attempt to determine the impact this polymorphism exerts on ovarian cancer." (PMID 26526682, 2015). "Some studies have suggested that low ERCC2 expression is associated with increased chemotherapeutic sensitivity and thus considered a predictive marker for patients with ovarian cancer receiving combination gemcitabine and cisplatin chemotherapy." (PMID 26526682, 2015). "In the reported study, the interest of the authors was focused onto the studies of the Lys751Gln polymorphism of ERCC2 gene in a group of patients with ovarian cancer and in a group of healthy people." (PMID 26526682, 2015). "Our results are in line with the data from other reports, introducing an important role of ERCC2 Lys751Gln polymorphism in ovarian carcinoma occurrence." (PMID 26526682, 2015). "An association (OR 5.01; 95% CI 3.37–7.43; p < 0.0001) was found between the Gln/Gln genotype of the Lys751Gln polymorphism of ERCC2 gene and ovarian cancer occurrence." (PMID 26526682, 2015). "Similar to our observation, the recent reports demonstrate that ERCC2 Lys751Gln genotype seems to be associated with an elevated ovarian cancer risk." (PMID 26526682, 2015). "A tendency for an increased risk of ovarian cancer progression was observed with the occurrence of Gln allele (OR 6.59; 95% CI 4.27–10.19; p < 0.0001) of ERCC2 polymorphism." (PMID 26526682, 2015). "From the current point of view, it seems to be more important to analyze the studies focusing on the effect of ERCC2 Lys751Gln polymorphisms in ovarian cancer." (PMID 26526682, 2015). "The Lys751Gln polymorphism of ERCC2 gene was selected on the basis of literature data, which are highly suggestive of its correlations with ovarian cancer." (PMID 26526682, 2015). "Heterozygous ERCC2 Lys751Gln exhibited a higher risk for ovarian cancer when age at menarche was before 13 years, BMI < 25 and WHR < 0.85." (PMID 18454848, 2008).